SMUG1 (single-strand-selective monofunctional uracil-DNA glycosylase 1)
Diseases named in the same sentence as SMUG1 in open-access papers:
SMUG1 is named in the same sentence as 28 diseases in open-access papers, as found by Europe PMC text mining. Sharing a sentence is not in itself a finding about the gene and the disease. The quoted sentences say what the papers report.
breast carcinoma (5 papers, 2014 to 2025). "Base excision repair proteins including XRCC1, APE1, SMUG1, and FEN1 were significantly associated with poor breast-cancer-specific survival." (PMID 39199284, 2024). "Low XRCC1 (p<0.01), low APE1 (p<0.01), low SMUG1 (p<0.01), and high FEN1 (p<0.01) remain independently associated with poor breast cancer-specific survival (BCSS)." (PMID 25111287, 2014). "Key base excision repair (BER) proteins, including XRCC1, APE1, SMUG1, and FEN1, were independently associated with poor breast cancer-specific survival (BCSS) (ps≤0.01)." (PMID 25111287, 2014). "SMUG1 is frequently overexpressed in breast cancer tissues and cancer cell lines." (PMID 41303849, 2025).
cervical cancer (3 papers, 2019 to 2025). A primary or metastatic malignant neoplasm involving the cervix. "In addition, increased expression of SMUG1 is often found in various tumor types (including bladder, gastric, breast, esophageal, and cervical cancers) with adverse clinicopathological features, such as poorly differentiated and chemoradiotherapy-resistant tumors." (PMID 31572446, 2019). "Few studies have examined LIG1, SMUG1, and TDG in CIN and cervical cancer." (PMID 35379200, 2022).
colon cancer (3 papers, 2018 to 2021). "Although the genes predicting poor survival that were identified in this study were 10, only mutations in NBN and SMUG1 turned out to be significant in multivariate analysis and thus can be considered independent prognostic factors for colon cancer patients." (PMID 29844865, 2018). "Mutations in SMUG1 have also been associated with poor prognosis in colon cancer." (PMID 33671338, 2021). "Additionally, low SMUG1 expression and mutations in SMUG1 are associated with poor prognosis in breast and colon cancer, respectively." (PMID 33671338, 2021). "Moreover, three patients with inactivating mutations in SMUG1 (Q93K, R187*, and R220W) demonstrated a 33% four-year survival rate after colon cancer diagnosis, compared to over 90% survival in patients without the mutations." (PMID 33671338, 2021). "Among clinically relevant genes, NBN and SMUG1 were identified as independent prognostic factors that predicted poor survival in colon cancer patients." (PMID 29844865, 2018).
colorectal cancer (3 papers, 2006 to 2019). A primary or metastatic malignant neoplasm that affects the colon or rectum. "Further study has shown increased survival in colorectal cancer for carriers of the genotype SMUG1 rs2233921 TT compared with those with the GT/GG genotypes." (PMID 31572446, 2019).
ovarian carcinoma (3 papers, 2016 to 2019). A malignant neoplasm originating from the surface ovarian epithelium. "XPC, SMUG1, and GTF2H5 were the top 3 most significant genes associated with ovarian cancer survival according to the prognostic signature." (PMID 31572446, 2019).
depression (2 papers, 2018 to 2025). "The functional polymorphism located in UNG modulated the occurrence and the onset of depression, and the SMUG1 SNP affected the time of the first episode." (PMID 29967751, 2018). "Regarding the effect of combined genotypes, it was found that the T/T-A/A-G/C (DUT (rs4775748), SMUG1 c.-31A>G (rs3087404) and UNG (rs34259) carriers had an increased risk of depression, whereas the T/G-A/G-G/G carriers had a reduced risk." (PMID 29967751, 2018).
lung carcinoma (2 papers, 2023 to 2024). "Among these genes, six were already identified in the lung cancer related network of genes associated with RETC634Y signature (TMEM45B, CLDN1, TRIM29, SMUG1, SATB2, and EFNA3)." (PMID 38132167, 2023).
B cell lymphomas (1 paper, 2017). "Furthermore, UNG and SMUG1 expression has recently been found to correlate negatively with genomic uracil levels in B cell lymphomas." (PMID 28362259, 2017).
bone lymphoma (1 paper, 2019). "SMUG1 is a key enzyme involved in BER that functions by removing uracil from single- and double-stranded DNA and is always associated with rectosigmoid junction neoplasms and bone lymphoma." (PMID 31572446, 2019).
breast tumors (1 paper, 2023). "Previously, we have shown that low RECQL breast tumors were significantly associated with low PARP1, BRCA1 negative, low RAD51, low ATM, low nuclear pChk1, low nuclear Chk2, low XRCC1, low FEN1, low SMUG1, and low DNA-PKcs expression." (PMID 38134458, 2023).
gastric cancer (1 paper, 2020). A primary or metastatic malignant neoplasm involving the stomach. "UNG and SMUG1 are overexpressed in non-small cell lung cancer and there is also evidence that SMUG1 is highly expressed in gastric cancer and this is correlated with poor survival." (PMID 33287345, 2020).
glioma (1 paper, 2022). A benign or malignant brain and spinal cord tumor that arises from glial cells (astrocytes, oligodendrocytes, ependymal cells).
lymphoid tumours (1 paper, 2017). "However, two cases of lymphoid tumours (more than 80% clonal based on TCR rearrangements) were previously found in a cohort of aged Smug1tm1a(EUCOMM)Hmgu−/−Ungtm1Tld−/− mice (hereafter referred to as UNG/SMUG1-DKO) at about 2 years of age12." (PMID 28775312, 2017).
melanoma (1 paper, 2017). A malignant, usually aggressive tumor composed of atypical, neoplastic melanocytes. "For melanoma samples, we further deduct C→T mutations in a CC context, as potentially induced by UV light (Material and methods: Enrichment of G→A mutations in SMUG1 mutated samples)." (PMID 28362259, 2017).
mental disorder (1 paper, 2018). A disease that has its basis in the disruption of mental process. "Table presents a distribution of genotypes and alleles of DUT g.48346598G>T (rs4775748), SMUG1 c.-31A>G (rs3087404) and UNG g.7245G>C (rs34259) single-nucleotide polymorphisms, and OR with 95% CI in groups of patients with rDD and controls without mental disorders." (PMID 29967751, 2018).
cancer (16 papers, 2014 to 2025). A tumor composed of atypical neoplastic, often pleomorphic cells that invade other tissues. "Growing evidence demonstrates that SMUG1 expression influences cancer susceptibility as well as response to treatment." (PMID 41303849, 2025). "Another significant cancer-associated gene in our analyses was SMUG1, a glycosylase that removes damaged uracil in the base excision repair pathway." (PMID 27602958, 2016). "Multiple single-nucleotide polymorphisms (SNPs) in SMUG1 have been suggested as independent prognostic factors associated with poor survival in patients with cancer of the colon, breast, bladder, and cervix, but the mechanisms underlying these associations are not known." (PMID 41394509, 2025). "Whether a similar mechanism is relevant in cancer cells remains to be defined, but a role for SMUG1 in gene regulation might explain other associations with SMUG1 and metabolic homeostasis." (PMID 41394509, 2025). "This review highlights the multiple roles SMUG1 may play in preserving genome stability, and how the loss of SMUG1 activity may promote cancer." (PMID 33671338, 2021). "Some studies suggest a loss of SMUG1 increases susceptible to cancer development." (PMID 33671338, 2021). "Based on these mice results, it might be expected that alterations in SMUG1 levels might be associated with human cancer." (PMID 33671338, 2021). "With a possible cancer relevance of SMUG1 emerging, it will be important to develop technologies that enable precise tracking of SMUG1 localization in vivo, particularly in relation to the replication fork." (PMID 41394509, 2025). "This demonstrates that there is much still to be elucidated about how SMUG1 functions to maintain genomic stability in the face of cancer therapy and endogenous replication stress." (PMID 41394509, 2025). "We previously showed that, in human cells, SMUG1 is part of a gene regulatory network involving a regulatory loop with the let-7b-5p miRNA that influences survival and treatment response in several cancers." (PMID 41394509, 2025). "SMUG1 has been shown to influence cancer cell survival, especially in response to nucleoside analogues." (PMID 41394509, 2025). "Recently, genetic interactions have been described between SMUG1 and proteins that safeguard stressed replication forks, implicating a function for SMUG1 in cancer cell biology." (PMID 41394509, 2025). "It is important to note that these human studies comparing SMUG1 levels to cancer were only correlative." (PMID 33671338, 2021). "This review then describes the genomic consequences when SMUG1 expression and activity are lost, and these implications in cancer." (PMID 33671338, 2021). "Another paper from the same group characterized the relationship between SMUG1 and a common cancer therapeutic, 5-fluoruracil (5-FU)." (PMID 33671338, 2021). "Five genes, UNG, SMUG1, MBD4, TDG, and DUT, are involved in the repair and prevention of uracil misincorporation into DNA, an anomaly that can lead to cancer-causing mutations." (PMID 30679536, 2019). "From studies in cancer cell lines, however, conditions where SMUG1 may influence cellular responses to chemotherapy are emerging." (PMID 41394509, 2025). "We also highlight the emerging role of SMUG1 in cancer cells and its potential as a therapeutic target, emphasizing the need to define the genetic and molecular contexts in which its modulation may be beneficial." (PMID 41394509, 2025).
cancer (continued). "The correlation between SMUG1 and cell survival may also reflect an indirect role of SMUG1 in cancer development." (PMID 41394509, 2025). "However, the first pharmacological targeting of SMUG1 in cancer cell lines showed that SMUG1 activation reduces toxicity to the same degree as SMUG1 knockouts." (PMID 41394509, 2025). "Notably, REV1- Polζ was recently identified to have a protective and mutagenic role in BRCA1/2 mutant cancer cells by filling in PRIMPOL-dependent ssDNA gaps that arise in these cells upon replication fork stalling at SMUG1-mediated DNA lesions." (PMID 36075897, 2022). "Thus, decreased SMUG1 activity and/or decreased expression in different forms of cancer remains largely uncharacterized on a molecular level." (PMID 33671338, 2021). "We also demonstrated that the expression of UHRF1, SMUG1, TDG, and MBD1/2/3 presented the most significant positive correlation with other regulators and might be the risk factors for carcinoma formation." (PMID 34552879, 2021). "Somatic mutations in NBN and SMUG1 in cancer (CC) have not been reported so far, though NBN germ-line mutations predispose to increased risk of developing cancer." (PMID 29844865, 2018). "However, a pioneering study on pharmacological SMUG1 modulation in human cancer cell lines suggests that this might be simplistic." (PMID 41394509, 2025). "Here, we provide an overview of the current knowledge of SMUG1 in DNA repair—from its remarkable active site that can accommodate a wide range of lesions, its role in BER, emerging evidence of functions in cancer cells." (PMID 41394509, 2025). "To directly assess the effect of UNG and SMUG1 on the generation of SBS2 and SBS13a/b in cancer cells, we expressed UNG–GFP in BC-1 cells, and CRISPR–Cas9 deleted SMUG1 from BT-474 cells and UNG from BT-474 and MDA-MB-453 cells." (PMID 35859169, 2022).
tumor (14 papers, 2015 to 2025). "Some regions, such as between 115–127 Mbp on Chromosome 5 (purple region), were highly mutated in the MMR defective tumours, but had very low mutation loads in the UNG/SMUG1 tumours." (PMID 28775312, 2017). "After normalization by the frequency of the given trinucleotide in the genome, however, C > T transitions emerged as the dominating class of mutation in UNG/SMUG1-DKO tumours." (PMID 28775312, 2017). "To assess the impact of the combined loss of UNG and SMUG1 activity on the spectrum of mutations generated in vivo, we subjected these tumours to whole genome sequencing." (PMID 28775312, 2017). "After correction for trinucleotide frequency, we see that loss of MMR resulted in a general enrichment for C > T transitions in CpG contexts, but with a more pronounced skewing towards mutations at GpCpG trinucleotides compared to the UNG/SMUG1-DKO tumours." (PMID 28775312, 2017). "The trinucleotide plots revealed a striking non-uniform pattern where the C > T mutations occurred predominantly in NpCpG trinucleotides (mutated base is underlined) in the UNG/SMUG1-DKO tumours (respectively)." (PMID 28775312, 2017). "Regions containing many mutations in the UNG/SMUG1-DKO tumours tended to have fewer exons, for example the region between 56–60 Mbp on chromosome 5 (grey region), perhaps indicating that BER has a global genome repair function." (PMID 28775312, 2017). "Given the well-established tumour-suppressive role of let-7 microRNAs, the association between SMUG1 expression and breast cancer prognosis may, at least in part, be independent of its canonical role in DNA repair." (PMID 41394509, 2025). "The current evidence points to potential therapeutic opportunities arising from exploiting SMUG1-mediated BER to induce synthetic lethality in combination with PARP and ATR inhibitors, particularly in BRCA1/2-deficient tumours." (PMID 41394509, 2025). "The expression levels of three writers (DNMT1, DNMT3A, DNMT3B), two erasers (TET1, TET3), and eight readers (MBD4, ZBTB33, UHRF1, UHRF2, UNG, TDG, NTHL1, SMUG1) were dramatically higher in tumor tissues (p < 0.05)." (PMID 38317133, 2024). "Outside of uracil, SMUG1 primarily works on 5-hmdU, a lesion which has been demonstrated to be elevated in tumor cells." (PMID 33671338, 2021). "The overrepresentation of C > T transitions at CpG dinucleotides in UNG/SMUG1-DKO tumours was surprising as these are generally interpreted as resulting from 5-methylcytosine, which deamination product, thymidine, is not recognised by either SMUG1 or UNG." (PMID 28775312, 2017). "Whole genome sequencing of UNG/SMUG1-deficient tumours revealed that combined UNG and SMUG1 deficiency leads to the accumulation of mutations, primarily C to T transitions within CpG sequences." (PMID 28775312, 2017).
tumor (continued). "Interestingly, C > A and C > G mutations did not retain the NpCpG context bias as was observed in the UNG/SMUG1-DKO tumours, but was instead occurring mostly in NpCpT contexts." (PMID 28775312, 2017). "Unfortunately, we cannot separate the relative roles of UNG and SMUG1 in mutation avoidance because neither of our single knockout mice developed tumours under SPF conditions." (PMID 28775312, 2017). "Further investigation illustrated that DNMT1/3A/3B, TDG, SMUG1, UNG, NEIL1, MDB3/4, ZBTB33, and UHRF1/2 were essentially upregulated in tumor samples, while TET2, MBD1, and MBD2 were downregulated in tumor samples." (PMID 35205097, 2022). "Several DNA5mC regulators were found to be significantly overexpressed in tumor tissues, including DNMT1, DNMT3B, TET2, TET3, MBD1, and SMUG1." (PMID 36425533, 2022). "Under a hypothesis that enzyme inhibition recapitulates enzyme knockdown and activation overexpression, one may expect a possible utility for SMUG1 activators or inhibitors in adjuvant settings, e.g. to sensitize HRD tumour to PARPi or ATRi, respectively." (PMID 41394509, 2025). "The DNA repair activity of multiple lesion-specific DNA glycosylases, such as MPG, SMUG1, UNG, NTH1, NEIL1 and OGG1 could be readily detected in lysates from human tumor cells (LN428, U2OS and K562 cell lines) and normal cells (PBMCs)." (PMID 30167090, 2018). "The fact that C to T transition mutations were the dominating class of mutation found in the two UNG/SMUG1-deficient tumours showed that neither the other UDGs nor the MMR pathway are able to fully compensate for the loss of UNG and SMUG1 in U:G repair at CpG dinucleotides." (PMID 28775312, 2017).
infection (3 papers, 2012 to 2020). The state of being infected such as from the introduction of a foreign agent such as serum, vaccine, antigenic substance or organism. "Among them, several genes encoding for enzymes involved in DNA metabolism were induced upon infection, such as DNA polymerases POLK and POLB, DNA helicase RECQL, and DNA glycosylase SMUG1 involved in various types of DNA repair, including mismatch repair, base excision repair, and direct repair." (PMID 24812617, 2014).
SMUG1 also shares sentences with these, for which no sentence is quoted: age-related macular degeneration (1 paper); cervical squamous cell carcinoma (1); diabetes (1); non-small cell lung carcinoma (1); Obesity (1); pancreatic cancer (1); rectosigmoid junction neoplasm (1); sarcoma (1); schizophrenia (1); uterus cancer (1).